SIGLEC1 (sialic acid binding Ig like lectin 1)
Diseases named in the same sentence as SIGLEC1 in open-access papers (continued):
Sharing a sentence is not in itself a finding about the gene and the disease.
infection (136 papers, 2012 to 2026). The state of being infected such as from the introduction of a foreign agent such as serum, vaccine, antigenic substance or organism. "Recent studies show that blockage of Siglec-1 on monocyte-derived dendritic cells (MDDCs) decreased SARS-CoV-2 viral transfer or trans-infection to bystander target cells, and Siglec1 was associated with disease severity and enhanced SARS-CoV-2 infection and influenced neutralizing antibodies." (PMID 36656015, 2023). "Infection of Siglec‐1‐deficient mice with RSV may give more insight into the role of Siglec‐1 during RSV infection in vivo." (PMID 29266251, 2018). "CD123+ ASDCs in blood have been reported to be permissive to infection via their expression of the HIV binding receptor CD169/Siglec-1 and they can transfer HIV to T cells." (PMID 38924030, 2024). "SIGLEC1 is highly expressed on mature DCs and mediates the trans-infection of HIV-1 to CD4+ T cells." (PMID 36726758, 2023). "The angiotensin-converting enzyme-2 (ACE-2) is a receptor for SARS-CoV-2, while surface lectins such as CD169 (also known as SIGLEC1) enhance ACE-2-dependent infection." (PMID 35072206, 2022). "Infection of SIGLEC1 null pigs with Type II PRRSV resulted in a productive infection as demonstrated by the presence of both circulating virus nucleic acid and viable virus." (PMID 35755158, 2022). "C-type lectins (DC-SIGN and L-SIGN) and sialic acid-binding immunoglobulin-like lectin 1 (SIGLEC1) were shown to function as attachments receptors by enhancing ACE-2 mediated infection." (PMID 35820906, 2022). "In the SC, Siglec1 expression was increased by 71-fold at 1 wk, and 12-fold at 4 wks post-infection." (PMID 36490282, 2022). "The level of Siglec1 gene expression in the UB was a 2.6-fold increase at 1 wk, and 1.8-fold at 4 wks after the infection." (PMID 36490282, 2022). "SARS-CoV-2 can use the C-type lectin receptors such as DC-SIGN, L-SIGN and the sialic acid-binding immunoglobulin-like lectin 1 (SIGLEC1) as attachment receptors to facilitate its presentation to ACE2 receptor for viral trans infection." (PMID 36499463, 2022). "To assess the possible effect of the SIGLEC1 null variant in HIV‐1 related co‐infections, we searched for the co‐occurrence of infections in the Swiss HIV‐1 Cohort Study (SHCS)." (PMID 33489013, 2021). "This study assessed the impact of type I IFN on macrophage infection with L. infantum and L. donovani and the implication of sialoadhesin (Siglec-1/CD169, Sn) as an IFN-inducible surface receptor." (PMID 32582193, 2020). "In another example, in vitro studies of cells infected with porcine reproductive and respiratory syndrome virus (PRRSV) show that SIGLEC1 on macrophages is required for infection." (PMID 30315482, 2019). "Lymph- and blood-borne retroviruses exploit CD169/Siglec-1-mediated capture by subcapsular sinus and marginal zone metallophilic macrophages for trans-infection of permissive lymphocytes." (PMID 30595553, 2019). "The expression of Siglec‐1 was higher in infants during the acute phase of infection compared to infants in the recovery phase, which suggests a temporal induction of Siglec‐1 during RSV infection." (PMID 29266251, 2018). "Trans-infection is largely dependent on the expression of the sialic-acid binding I-type lectin receptor Siglec-1 (CD169 or Sialoadhesin)." (PMID 29209326, 2017). "SIGLEC-1 expression on monocytes has been previously proposed as an interferon-induced biomarker of infection, vaccine response or disease activity." (PMID 28815218, 2017). "Here, we aimed to identify SIGLEC1 null individuals to dissect the specific contribution of trans-infection to HIV-1 pathogenesis in vivo." (PMID 27510803, 2016). "The results indicated that SIGLEC1 expression could significantly enhance the infection by all the coronaviruses tested." (PMID 36726758, 2023).
infection (continued). "To investigate if SIGLEC1 could enhance the infection of SARS-CoV-2 in AMs, we isolated the primary AMs from human BAL fluid with noninflammatory or noninfectious disorders." (PMID 36726758, 2023). "However, overexpression of SIGLEC1 in ACE2-knockout HeLa still promotes the infection, albeit much less efficient than that in wild-type HeLa cells, suggesting that the role of SIGLEC1 in promoting SARS-CoV-2 infection primarily depends on the receptor ACE2." (PMID 36726758, 2023). "Recently, it was demonstrated that attachment to such receptors as CLRs, DC-SIGN, L-SIGN, and sialic-acid-binding immunoglobulin-like lectin 1 (SIGLEC1) enhances ACE2-mediated infection and modulates the neutralizing activity of distinct types of spike-specific antibodies." (PMID 35847031, 2022). "SIGLEC1, sialic acid binding Ig-like lectin 1, is involved in initial contact with sialylated pathogens and mediates phagocytosis and endocytosis of pathogens, thereby promoting immune responses to limit infection." (PMID 36544770, 2022). "In addition, rIFN-β induced Siglec1 (CD169), which is associated with macrophages that produce type-I IFNs during an infection." (PMID 34149716, 2021). "In turn, the functional study of naturally occurring human ‘knockouts’ in infectious contexts may identify novel host factors, such as Siglec‐1, which illuminate previously unknown pathways that modulate complex infections such as TB." (PMID 33489013, 2021). "RSV‐induced expression of Siglec‐1 may be present on recruited monocytes and/or resident macrophages to regulate T cell functionality at the site of infection." (PMID 29266251, 2018). "Recent data indicate that pre-DCs may be one of the key circulating myeloid cell subsets capable of productive infection and trans-infection as they constitutively express CD169/Siglec-1; as such, they may constitute a promising cell type to investigate when studying trans-infection." (PMID 32181159, 2020). "In parallel, the infection of AT2s, directly through binding to ACE2 or possibly through a trans-infection process mediated by SIGLEC1 expressed by macrophages, would produce viral progenies in the context of low anti-viral IFN response." (PMID 39147987, 2024). "In the trans-infection process, receptors such as DC-SIGN and SIGLEC-1 are involved, which are mainly expressed in immature DCs (iDCs) and mature (mDCs) DCs, respectively." (PMID 35802715, 2022). "In addition, CD169, which is also known as sialoadhesin or sialic acid-binding immunoglobulin-like lectin-1 (Siglec-1), is exclusively expressed on specific subpopulations of macrophages and is considered to be an accessory protein involved in the infection process of the PRRSV." (PMID 33447967, 2021). "It has been reported that high expression of Siglec-1 (CD169) on DC matured with lipopolysaccharide (LPS) and type I interferon (IFN) significantly contributes to trans infection, and its importance in retrovirus infections has been shown in a mouse model." (PMID 33688006, 2021). "One explanation for how SIGLEC-1 knockout pigs can support infection is based on the presence of alternative SIGLEC proteins, such as SIGLEC-10, which can substitute for the SIGLEC-1 protein." (PMID 30658381, 2019). "The next highest scoring hit is SIGLEC1/CD169, an HIV attachment factor that has been characterized to facilitate trans infection of CD4 +T cells by DCs through binding to sialylated glycosphingolipids on the HIV particle." (PMID 30520725, 2018). "Siglec-1/CD169 is a myeloid-cell surface receptor critical for HIV-1 capture and infection of bystander target cells." (PMID 27510803, 2016). "However, over-expression of CD163 and Siglec1 in combination was required for productive infection, indicating a synergistic role for these proteins in ASFV cell entry and infection." (PMID 40692871, 2025). "The peak and duration of infection in SIGLEC1 null pigs were no different from SIGLEC1 heterozygous or wild-type littermates." (PMID 35755158, 2022).
infection (continued). "CD169 (Siglec-1) facilitates the capture of retroviruses by macrophages lining the sinus region of lymph nodes and its passage to B cells within follicles, as well as HIV-1 trans infection by DC." (PMID 29643243, 2018). "We demonstrate that the HIV attachment factor, SIGLEC1/CD169, plays a role in enhancing infection in THP-1 cells in cis rather than the more fully described role of SIGLEC1 to mediate infection from dendritic cells to T cells in trans." (PMID 30520725, 2018). "This viral hijacking mechanism does not rely on productive myeloid cell infection but requires HIV-1 capture via Siglec-1/CD169, a receptor expressed on myeloid cells that facilitates the infection of bystander target cells." (PMID 29209326, 2017). "Trans-infection was inhibited with a mAb against Siglec-1, which had no blocking effect on SIGLEC1 null monocytes." (PMID 27510803, 2016). "While a null of SIGLEC1 did not prevent infection, the SIGLEC1 protein may be redundantly involved in viral attachment to the PAM." (PMID 35755158, 2022). "Finally, our results suggest that calcitriol can decrease the protein expression of SIGLEC-1 and DC-SIGN, receptors widely related to trans-infection, suggesting that this is at least one of the possible mechanisms by which calcitriol reduces viral transfer to CD4+ T cells." (PMID 35802715, 2022).
cancer (48 papers, 2016 to 2026). A tumor composed of atypical neoplastic, often pleomorphic cells that invade other tissues. "Our study offers a fresh perspective on CRC prognosis and therapy, with implications that extend beyond SIGLEC1 itself to the broader field of cancer immunology and TCM-based anticancer therapies." (PMID 39744582, 2025). "SIGLEC1 (also known as CD169), is also abnormal expression in peripheral macrophages of many cancers, especially in the lymph node." (PMID 33408717, 2020). "Cancer tissues had higher numbers of macrophages per mm2 tissue area, and a higher percentage of SIGLEC1+ cells compared with benign tissue; results that were further confirmed by confocal microscopy of the stained sections." (PMID 30930117, 2019). "We performed in vitro co-culture to demonstrate that interactions between hypersialylated cancer cells and Siglec1 drive the proliferation of cancer cells." (PMID 31872800, 2019). "Among the genes selected to construct the NR-signature, VSIG4, SIGLEC1, and CXCL13 showed significant correlations with immune microenvironment scores in pan-cancer." (PMID 36544770, 2022). "In addition, this study found that DEGs in the three groups were also enriched in cancer and certain disease pathways (TNFSF10, ACKR4, FLT3, SIGLEC1, etc.)." (PMID 40282783, 2025). "We further identify SIGLEC-1,15 and CD22 as hub genes in COAD through Differentially Expressed Genes (DEGs), which is consistent with our PCA-identified key components PC-1,2,5 considering both the correlation with cancer status and immune cell abundance." (PMID 38650859, 2024). "Exosomes secreted from ST3G5high cancer cells (ST3G5high‐cExos) were found to contain high levels of hypoxia‐inducible factor 1‐alpha (HIF1α) and accumulated in MSs via uptake in macrophages (MΦs) owing to increased expression of sialic acid‐binding Ig‐like lectin 1 (CD169; also known as SIGLEC1)." (PMID 37716915, 2024).
infectious disease (3 papers, 2018 to 2025). A disorder directly resulting from the presence and activity of a microbial, viral, or parasitic agent in humans. "To evaluate if the SIGLEC1 null variant was over‐represented in any particular infectious disease category, we used a hypergeometric test." (PMID 33489013, 2021). "The low expression of CD43 on newborn CD4+ T cells and the inhibitory role of Siglec‐1 in adults could therefore have multiple implications on T cells during infectious diseases." (PMID 29266251, 2018).
connective tissue diseases (1 paper, 2022). "When compared to other connective tissue diseases (CTDs) SIGLEC-1 expression was highest in SLE (8761.66 ± 8325.74), followed by MCTD (6414.50 ± 1846.55) and pSS (4371.69 ± 4227.89)." (PMID 36297311, 2022). "SIGLEC-1 expression on monocytes can be useful in the differential diagnosis of connective tissue disease but not as a biomarker for SSc disease manifestations or activity." (PMID 36297311, 2022).
neurodegenerative disease (1 paper, 2020). A disorder of the central nervous system characterized by gradual and progressive loss of neural tissue and neurologic function. "Siglec1 encodes for sialoadhesin, a membrane receptor of macrophages and activated monocytes, that was previously shown to promote neuroinflammation in neurodegenerative diseases." (PMID 31837604, 2020).
neurological diseases (1 paper, 2021). "Additionally, we histologically evaluated the presence of SIGLEC1+ myeloid cells in acute and chronic MS brain lesions as well as other neurological diseases." (PMID 33986412, 2021).
SIGLEC1 also shares sentences with these, for which no sentence is quoted: colitis (15 papers); bacterial infection (10); bladder cancer (7); lymph node metastasis (6); Autoimmunity (5); gastric cancer (5); rheumatoid arthritis (5); prostate carcinoma (4); AIDS (3); anemia (3); atherosclerosis (3); influenza infection (3); lung fibrosis (3); malaria (3); oral squamous cell carcinoma (3); pneumonia (3); Sepsis (3); bacteremia (2); breasts (2); esophageal cancer (2); Hepatitis (2); inflammatory bowel disease (2); Listeria monocytogenes infection (2); liver diseases (2); lung disease (2); lymphoma (2); myeloma (2); Obesity (2); osteosarcoma (2); parasitemia (2).
A further 90 diseases each share a sentence with SIGLEC1 in 2 papers or fewer.